TWIST1 (twist family bHLH transcription factor 1)
Diseases named in the same sentence as TWIST1 in open-access papers (continued):
Sharing a sentence is not in itself a finding about the gene and the disease.
glioma (continued). "Twist1, as a key regulator of EMT, has been found to be elevated during glioma migration." (PMID 35219305, 2022). "miR-361-5p could target Twist1 to inhibit EMT of gliomas cells and presents a downregulated level in gliomas." (PMID 34321465, 2021). "TCGA database analysis showed that ZEB1, ZEB2 and TWIST1 expression, but not E-Cadherin, were increased in glioma." (PMID 31429770, 2019). "When Twist1 is methylated by SETD6 (a methyltransferase), it will increase the occupancy of EZH2 (a histone lysine methyltransferase) and the catalysis of the repressive H3K27Me3 (histone H3 lysine 27 trimethylation) mark at the locus of lncRNA LINC-PINT (a tumor repressor in gliomas)." (PMID 36338770, 2022). "Besides, the expression of Twist1 was significantly increased from the WHO tumor grade II to grade IV, suggesting a correlation between the level of Twist1 and the malignant degree of glioma (One-way ANOVA, p = 1.22e-14)." (PMID 35219305, 2022). "In the present study, HDAC1 knockdown significantly increased the expression of BIM, BAX, cleaved CASPASE3 and E-CADHERIN, and suppressed the expression of TWIST1, SNAIL and MMP9, which could be interpreted to be pro-apoptosis and anti-invasion effects of HDAC1 shRNA in glioma cells." (PMID 28624794, 2017). "In addition, Twist1, an EMT inducer, was recently shown to co-regulate glioma stemness with Sox2." (PMID 29228694, 2017). "However, the impact of inhibiting Twist1 on tumorigenicity has not been characterized in glioma models in the context of different oncogenic transformation paradigms." (PMID 29296200, 2017). "We previously reported that TWIST1 (TW), a critical regulator of epithelial mesenchymal transition (EMT), metastasis and stem cell phenotypes in carcinomas, also promotes mesenchymal change and invasion in glioma cells and enhances self-renewal of human glioma stem-like cells (GSC) in vitro." (PMID 29296200, 2017). "However, the role of TWIST1 in promoting glioma invasion has not been investigated in the context of the brain microenvironment or as a mediator of mesenchymal change as occurs in carcinomas." (PMID 20646316, 2010). "Moreover, most EMT biomarkers, including N-cadherin, snail, slug, vimentin, TWIST1, and TWIST2, were significantly correlated with BDKRB2, which suggested that BDKRB2 might profoundly interact with these key molecules of EMT, further confirming the involvement of BDKRB2 in glioma EMT." (PMID 33686021, 2021). "As EMT induction factor, transcription factors, the expression of SNAI1, SNAI2, TWIST1, and PDGFB was significantly higher in high-grade, elderly glioma patients, IDH-wildtype, 1p19q non-codel glioma patients." (PMID 32154177, 2020). "With CIN genes, we observed a significant positive correlation in certain tumor types, which include kidney cancers, lower-grade glioma (LGG) and lung adenocarcinoma (LUAD); whereas, in stomach adenocarcinoma (STAD) a significant negative correlation was observed between Twist1 and CIN genes." (PMID 32337580, 2020). "However, the lack of a TWIST1-mediated "cadherin switch" in GBM cells suggested that alternative mechanisms in nervous tissue and gliomas function to modulate cell adhesion and invasion." (PMID 20646316, 2010). "Inhibitors of TWIST1 are not available; therefore, to investigate the therapeutic relevance of inhibiting TWIST1 in GBM we knocked down TWIST1 expression using shRNA and assayed its effects on cell invasion and glioma stem cell properties." (PMID 20646316, 2010).
breast tumor (50 papers, 2005 to 2025). "In this study, we found that high levels of PD-L1 expression are associated with TWIST1 expression in ER−/HER2− breast tumors and TNBC cell lines." (PMID 38893094, 2024). "TWIST1 expression is negatively correlated with Foxa1 in human breast tumors, and tumors with high TWIST1 and low Foxa1 expression are associated with poor distant metastasis-free survival." (PMID 32565805, 2020). "In particular, recent evidence has linked increased expression of EMT markers such as TWIST1 and MMPs in breast tumors with increased immune infiltration in the TME." (PMID 31075939, 2019). "Firstly, signal transducer and activator of transcription 3 (STAT3) is implicated in Twist1 regulation by the observation that Twist1 expression is ablated upon STAT-3 knockdown in breast tumors in immunocompetent mice." (PMID 28099910, 2017). "The up-regulated genes include CTNNB1, GSC and TWIST1, encoding for transcription factors known to be activated during breast tumor metastasis, and AHNAK and AKT1, variously involved in tumorigenesis and cell motility." (PMID 24962430, 2014). "The upregulation, methylation of TWIST1, and hormone treatment resistance in breast tumors have been reported." (PMID 38611109, 2024). "To assess the correlation of TWIST1 expression with its regulated genes in human breast tumors, we analyzed the METABRIC transcriptomic datasets downloaded from cBioPortal." (PMID 38893094, 2024). "RCC2 expression upregulated IL-6, IGF1, and TWIST1 expression both in animal models and in cultured ER + breast tumor cells." (PMID 32565805, 2020). "Examples are 269 TF knockout microarrays used for genome-scale investigation of eukaryotic gene regulation, Gata1 knockout to identify GATA1-responsive genes, and tumor cell-specific Twist1 knockout to study the effect of Twist1 on breast tumors in vivo." (PMID 31598675, 2020). "In breast tumors downregulation of SDH complex subunit C (SDHC) is associated with EMT, and expression of pro-EMT transcription factors Twist-related protein 1 (TWIST1) and Snail resulted in lower mitochondrial mass and respiration." (PMID 31552162, 2019). "MiR-720 was described to inhibit breast tumor invasion and migration by targeting the metastasis promoter TWIST1." (PMID 26728044, 2016). "In contrast, our results show that in breast tumor cell lines, TWIST1 stimulates NF-κB through the TWIST1 WR domain and up-regulates the expression of the NF-κB downstream target gene IL8." (PMID 22891766, 2012). "This altogether suggests that TWIST1 mRNA is predominantly expressed in the stromal compartment of breast tumor tissues." (PMID 22967435, 2012). "To address this in more detail, we stained 20 primary breast tumor tissues (n = 7 ER-negative and n = 13 ER-positive) for TWIST1 protein." (PMID 22967435, 2012). "To better understand the role of invadopodia and PDGFRα in metastasis, we utilized a subcutaneous tumor implantation model in which Twist1-expressing human breast tumor cells carrying shRNAs against PDGFRα or Tks5 were injected subcutaneously in nude mice." (PMID 21725138, 2011). "In addition, a recombinant TWIST1 protein has been used as a vaccine to induce both CD8+ and CD4+ TWIST1-specific T-cell responses in vivo to attack TWIST1-expressing breast tumor cells with certain efficacy." (PMID 38893094, 2024). "Furthermore, an examination of TWIST1 and PD-L1 protein expression profiles in individual cells of human breast tumor specimens will further validate the regulatory relationship between TWIST1 and PD-L1 as well as their prognosis relevance." (PMID 38893094, 2024). "Moreover, knockout of TWIST1 has been found to significantly reduce the number of Vimentin-positive breast tumor cells, which indicates that Twist1 expression is positively associated with Vimentin expression." (PMID 35052775, 2022).
breast tumor (continued). "To further examine the role of ID4 in cancer stemness, we knocked down ID4 in MDA-MB-468 breast tumor cells using SMARTpool siRNAs, and tested the expression of a panel of stemness genes including Twist1, Twist2, Snail, Slug, BMP2, IRF1, SOX4, Foxk1 and Notch3." (PMID 36291790, 2022). "In vivo subcutaneous xenotransplanted tumor model also revealed that over-expression of TFPI2 could suppress breast tumor growth via down-regulation of TWIST1-mediated integrin α5 expression." (PMID 32248791, 2020). "In triple negative breast cancer cells, garcinol was reported to sensitizes tumor cells to Taxol, which was mediated via suppression of caspase-3/cytosolic CA2+-independent phospholipase A2 (iPLA2) and NF-κB/Twist-related protein 1 (Twist1) pathway in mouse 4T1 breast tumor model." (PMID 32365899, 2020). "It has also been previously shown that in human breast tumors there is an inverse relationship between TWIST1 and ER expression that may possibly contribute to the generation of hormone-resistant, ER-negative breast cancer." (PMID 31261917, 2019). "It would be particularly interesting to determine the behavior of Twist1+ cells in 3D collagen I gels with defined rigidity and pore size, as collagen I provides a more physiologic model of the interstitial matrix surrounding breast tumors." (PMID 27402962, 2016). "Complexing YTZ3-15 with TWIST1 siRNA may therefore have the potential to allow delivery of potent siRNAs to breast tumor cells to reduce TWIST1-mediated expression of EMT target genes and inhibit metastatic potential." (PMID 25759817, 2015). "The seemingly contradicting data in normal mesodermal tissues and breast tumor cell lines may indicate there are additional players modifying the functional relationships between TWIST1 and RELA during different processes in development." (PMID 22891766, 2012). "This characteristic of IL8 may partially be responsible for TWIST1-associated tumor angiogenesis that was previously noted by our group and collaborators in TWIST1 over-expressing MCF7 breast tumor cells." (PMID 22891766, 2012). "Also in line with this is the increased lymph node involvement of breast tumors exhibiting higher TWIST1 expression as observed by us and others." (PMID 22967435, 2012). "The METABRIC database (1904 human breast tumors) consistently revealed a positive association of NME4 with epithelial markers CDH1 and KRT18 and a negative association with mesenchymal markers CDH2 and VIM as well as many EMT drivers like ZEB1, ZEB2, SNAI2, TWIST1, and TWIST2." (PMID 34674701, 2021). "We assessed the mRNA levels of TWIST1, SLUG, and SIP1 in human breast tumor samples from the Brazilian National Cancer Institute cohort." (PMID 34830027, 2021). "MAPKs can promote breast tumor cell EMT and metastasis via phosphorylation and stabilization of Twist1, and PLCε can regulate key molecules involved in MAPK expression." (PMID 31383001, 2019). "Twist1 is a master regulator of morphogenesis, which can induce EMT to facilitate breast tumor metastasis." (PMID 28774312, 2017). "In conclusion, in this prospective translational study, we showed for the first time a lack of association between CTCs in peripheral blood and expression of EMT-inducing transcription factors, TWIST1 and SLUG, in primary breast tumor tissue." (PMID 26194471, 2015). "In this translational study, we showed a lack of association between CTCs and expression of EMT-inducing transcription factors, TWIST1 and SLUG, in breast tumor tissue." (PMID 26194471, 2015). "The aim of this study was to assess correlation between CTCs and expression of EMT transcription factors TWIST1 and SLUG in breast tumor tissue." (PMID 26194471, 2015). "In this translational study, we showed lack of association between CTCs and expression of EMT-inducing transcription factors, TWIST1 and SLUG, in primary breast tumor tissue." (PMID 26194471, 2015).
breast tumor (continued). "We also have reported that only a small subset of primary mouse breast tumor cells but almost all circulating tumor cells express Twist1 and exhibit partial EMT, while the knockout of Twist1 can prevent these partial EMT and intravasation phenotypes from occurring in these tumor cells." (PMID 38893094, 2024). "Certainly, the mRNA expression of TWIST1 and ADAM12 is strongly correlated in human breast tumors, and the TWIST1 transcription factor promotes tumor invasion and metastasis by inducing epithelial-mesenchymal transformation and invadopodia-mediated degradation of the extracellular matrix." (PMID 34604068, 2021). "Additionally, another study found that Slug is a direct transcription target of Twist1 in the repression of E-cadherin during EMT, and these two transcription factors cooperatively promote EMT in human breast tumors." (PMID 27027434, 2016). "Mechanistically, NCOA1 has been shown to up-regulate Twist1, ITGA5, CSF-1, SDF1 and CXCR4 expression, which are partially responsible for promoting metastasis through potentiating breast tumor cell epithelial-mesenchymal transition (EMT), migration, invasion and macrophage recruitment." (PMID 26287601, 2015). "To determine the relevance of the in vitro mechanistic studies in relation to patient samples, we analyzed the relative expression levels of TWIST1 and IL8 in the STOCKHOLM (GSE1456) and UPPSALA (GSE3494) human breast tumor datasets (with a total of 412 samples from both datasets combined)." (PMID 22891766, 2012). "Along the same lines, our results suggest that patients suffering from breast tumors overexpressing Twist1 may not profit from therapies targeting TGFβ pathway components." (PMID 27105506, 2016). "Stemming from the observation that endogenous nuclear TWIST1 was found in aggressive human breast tumor samples, but not in distant metastatic lesions, the hypothesis that TWIST1 may be dynamically regulated in primary tumor versus distant metastasis was tested." (PMID 28085222, 2017).
osteosarcoma (48 papers, 2010 to 2025). A usually aggressive malignant bone-forming mesenchymal neoplasm, predominantly affecting adolescents and young adults. "PCOLCE is a direct transcriptional target of TWIST1 and it is implicated in the regulation of collagen deposition during both early craniofacial development and in osteosarcoma, where it promotes tumor growth, cell migration, and invasion." (PMID 35022561, 2022). "One example is upregulation of the histone deacetylase HDAC5 in osteosarcoma, which via its gene repressive function, activates downstream TWIST1 expression, a known oncogene and EMT driver." (PMID 40442778, 2025). "In a study using 83 osteosarcoma tissues, the expression of Snai1/Slug/Twist1 was correlated with that of EPB41L3." (PMID 37373330, 2023). "For example, SOX6 expression was decreased in osteosarcoma and exerted a suppressive effect on migration, invasion, and epithelial-mesenchymal transition by regulating TWIST1." (PMID 38062424, 2023). "For example, Twist1 promotes the metastasis of osteosarcoma by up-regulating the expression of PCOLCE." (PMID 36639679, 2023). "The LncRNA AFAP1-AS1 promotes tumorigenesis and epithelial-mesenchymal transition of osteosarcoma through the RhoC/ROCK1/p38MAPK/Twist1 signaling pathway." (PMID 35179516, 2022). "PCOLCE was overexpressed in osteosarcoma and promoted lung metastasis via twist family bHLH transcription factor 1 (TWIST1)." (PMID 35036081, 2022). "It has been reported that TWIST1 signaling is involved in lncRNA AFAP1-AS1-induced osteosarcoma tumorigenesis and EMT." (PMID 34224315, 2021). "HDAC5 induced osteosarcoma cell proliferation in a Twist1-dependent manner, highlighting the varied functions of the HDAC5/Twist1 axis in tumor progression." (PMID 34178647, 2021). "This study demonstrates lncRNA AFAP1-AS1 is overexpressed in osteosarcoma and plays an oncogenic role in osteosarcoma through RhoC/ROCK1/p38MAPK/Twist1 signaling pathway, in which RhoC acts as the interaction target of AFAP1-AS1." (PMID 31443665, 2019). "In our study, AFAP1-AS1 knockdown downregulated the expression levels of RhoC, ROCK1, phosphorylated p38MAPK, and Twist1 in osteosarcoma cells." (PMID 31443665, 2019). "In osteosarcomas, it has been demonstrated that TWIST1 expression provides osteosarcoma cells resistance to chemotherapy, whereas downregulation of SLUG induces a decrease of migration." (PMID 30509303, 2018). "Consistently, a subsequent study found that miR-33a promotes osteosarcoma cell resistance to cisplatin by down-regulating Twist1." (PMID 28099910, 2017). "The Cyr61 protein promoted the mesenchymal transition of osteosarcoma cells by upregulating mesenchymal markers (TWIST-1 and N-cadherin) and inhibiting the epithelial marker (E-cadherin)." (PMID 25326651, 2014). "Substantial evidence has indicated that osteosarcoma exhibits EMT-like states, characterized by changes in the expression of EMT-related transcription factors, such as TWIST-1, snail, and ZEBs, which are involved in the complex pathogenesis of osteosarcoma." (PMID 25326651, 2014). "CDK5 and TWIST1 have been reported to increase metastasis and are upregulated in osteosarcoma tumors with low levels of 14q32 miRNAs." (PMID 23311495, 2013). "TWIST1 overexpression was reported in a variety of solid cancers including breast, prostate and gastric carcinomas, melanomas, osteosarcomas, rhabdomyosarcomas, as well as in Sezary syndrome." (PMID 21037858, 2010). "However, circRAB3IP reduces miR-580-3p expression to upregulate Twist1 and promote osteosarcoma malignancy." (PMID 38733529, 2024). "miR-580-3p is an inhibitor of Twist1, which reduces the malignancy of osteosarcoma cells." (PMID 38733529, 2024). "PCOLCE is upregulated by TWIST1 in osteosarcoma and promotes osteosarcoma metastasis to the lung." (PMID 37197432, 2023). "Moreover, at the cellular level, miR-22 overexpression impaired proliferation and EMT in osteosarcoma by targeting Twist1." (PMID 34368151, 2021).